ALB (albumin)
Diseases named in the same sentence as ALB in open-access papers (continued):
Sharing a sentence is not in itself a finding about the gene and the disease.
tumor (continued). "The variables included in the ISS are similar to previously identified scores including markers of liver function such albumin, bilirubin, and tumor burden." (PMID 27601241, 2016). "In the current study, tumor stage and albumin level (P < 0.001) were also shown to be independent prognostic factors of decreased OS." (PMID 27510632, 2016). "We also evaluated the possibility to use the human albumin, produced by Huh-7 cells, as a serum marker of tumor growth." (PMID 27739457, 2016). "Univariate and multivariate analyses showed that tumor stage, palliative care, albumin level, and pretreatment NLR (HR: 1.514, 95% CI: 1.125~2.038, P = 0.006) were independent prognostic indicators of OS." (PMID 27510632, 2016). "In Group III, lower albumin (p = 0.048) and tumor numbers ≤ 3 (p = 0.023) presented significant difference affecting patient’s survival." (PMID 27117280, 2016). "Albumin, platelets and lymphocytes play different roles in systematic inflammation which leads to tumor progression." (PMID 26885692, 2016). "For optimizing the acquisition protocol, amino acids, Gelofusine, fragmented albumin or other substances should be used for blocking tracer uptake by proximal kidney tubules, because of a very high kidney to non-tumor ratio." (PMID 27526057, 2016). "Depending on the modelling approach applied, albumin, body surface area, neutrophil, baseline tumour size and tumour shrinkage measures were identified as potential prognostic factors." (PMID 26940939, 2016). "For example, in the Tokyo Score, 4 markers, albumin, bilirubin, tumor size, and the number of tumors, are used." (PMID 27800494, 2016). "In this strategy, a trastuzumab-based first component was used to pre-label the HER2(+) tumor cells and a paclitaxel-loaded albumin carrier was subsequently delivered as the cytotoxic treatment component." (PMID 27068794, 2016). "When considered with tumor-related systematic inflammation, the ability of the liver to produce albumin decreases as a result of increased acute-phase protein synthesis." (PMID 27344157, 2016). "In our survival analysis, we considered patient-related parameters (pre-operative serum albumin level; pre-operative serum neutrophils to lymphocytes and platelets to lymphocytes ratio) and tumor-related factors (PCI; primary tumor site, CC score)." (PMID 27036213, 2016). "After controlling for tumor stage, primary tumor site, palliative care, nutritional status, and albumin level, NLR (HNLR vs. LNLR) remained significantly (HR: 1.514, 95% CI: 1.125~2.038, P = 0.006) associated with OS." (PMID 27510632, 2016). "Several markers have been reported to reflect the association of inflammation and tumor, such as interferon-gamma/interleukin-4 ratio and inflammation-based prognostic score based on CRP and albumin levels." (PMID 27125872, 2016). "If a patient has an albumin value of 3.0 g/dL, bilirubin value of 1.5 g/dL, tumor size of 1.0 cm, and the number of tumors of 4, the score values of each marker are 1 point, 1 point, 0 points, and 2 points, respectively, resulting in a total score of 4 points." (PMID 27800494, 2016). "Both tumour-bearing groups (W and LW) exhibited a decrease in the rat carcass weight, a tumour weight to body weight ratio higher than 10 % and a reduction in serum albumin concentration." (PMID 27716121, 2016). "For patients with resectable PDAC, preoperative CRP, along with albumin and tumour markers, is useful for predicting prognosis." (PMID 27632196, 2016). "Receiver operating characteristic (ROC) curve analysis determined 200 mg/L, 120 g/L, 5 cm, and 51 as the cutoff values of pre-albumin, hemoglobin, tumor size, and PNI, respectively." (PMID 27809860, 2016). "Advanced tumor stage was associated with a poorer histologic differentiation, higher CRP level, lower albumin level, and inferior progression‐free survival rate (PFSR)." (PMID 26799163, 2016).
tumor (continued). "Upon administration the linker is thought to bind to circulating albumin and is, therefore, transported to the tumour site where the acidic environment will cleave the linker and release doxorubicin to exert its action." (PMID 26925240, 2016). "Above all, baseline tumor characteristics before hepatectomy have a significant impact on patient prognosis, including serum alpha-fetoprotein (AFP) and albumin, and platelet count has been associated with tumor recurrence and OS in HCC patients." (PMID 27506942, 2016). "A major limitation of our study is that the influence factor of HCC prognosis is variable, such as the Albumin-Bilirubin (ALBI) score, tumor differentiation, race, pathogenic factors, and so on." (PMID 27835609, 2016). "Based on multivariate analysis of the entire cohort, independent factors for OS were tumor size, tumor capsule, pathological grades, total bilirubin, albumin, prothrombin time, alpha-fetoprotein, and tumor number, which were incorporated into the nomogram." (PMID 25776856, 2015). "ECOG performance status, concurrent VI and Mets, tumor size, serum AFP, bilirubin, creatinine, albumin, and AST levels were baseline factors associated with OS." (PMID 25860213, 2015). "These qualities are demonstrated by superior tumor targeting by serum albumin and streptavidin over tumor-specific Fab fragments." (PMID 25901755, 2015). "The HAP score is a simple scoring index requiring the measurement of two tumor variables (alpha-fetoprotein and the largest size of tumor) and two liver variables (albumin and bilirubin) and can predict outcomes in transcatheter arterial embolization/TACE." (PMID 25919025, 2015). "Nab-paclitaxel is albumin-bound paclitaxel that increases tumor accumulation of paclitaxel through binding of albumin to the stroma rich in overexpression of SPARC." (PMID 25935754, 2015). "Streptavidin and serum albumin had almost identical temporal kinetics of tumor uptake, yet serum albumin is ~30% larger in molecular weight." (PMID 25901755, 2015). "Since intratumor heterogeneity is a major clinical problem of cancer therapies, the current study focused on BACS based on targeted albumin MBs to isolate different tumor cell subtypes." (PMID 25993512, 2015). "This system consists of four factors: tumor size, number of tumor nodules, serum albumin and bilirubin." (PMID 25524574, 2015). "Proliferating tumor cells actively take up albumin via endocytosis where it is catabolized, and the derived amino acids are used for de novo protein synthesis, energy and growth." (PMID 26231955, 2015). "Considering the increased distribution of albumin in the tumor interstitium and the crucial role of this protein as a drug shuttle, it was critical to evaluate the interaction between Dp44mT and albumin." (PMID 25848850, 2015). "Multivariate analysis of the prognostic factors found that maximum tumor size (>5 cm) (HR: 2.05; 95% CI: 1.36–3.10; P = 0.001) and albumin (≤3.4 g/dL) (HR: 2.10; 95% CI: 1.36–3.26; P = 0.001) were significantly associated with poor prognosis." (PMID 26044168, 2015). "Albumin is highly accumulated in tumors, as tumor cells use albumin as a major energy and nitrogen source through endocytosis and lysosomal degradation." (PMID 26231955, 2015). "One of the most important features of the albumin based drug delivery system is the enhanced drug accumulation in tumor tissues due to the leaky vasculature of the angiogenic vessels in solid tumor." (PMID 25890381, 2015). "Albumin-Cre/MST1fl/fl/MST2fl/fl mice are an HCC model that develops hypervascular masses with rich tumor-supplying arteries." (PMID 26131558, 2015). "It was observed that the presence of albumin on the exterior of the bPEI-siRNA polyplexes dramatically improve uptake and gene silencing in both human endothelial and tumor epithelial cells." (PMID 25856158, 2015).
tumor (continued). "The strongest predictors of longer survival were ECOG performance status 0 to 1 (HR 1.95), fewer than 6 active tumors (HR 2.70), favorable primary tumor site (HR 3.33) and normal serum albumin (HR 2.09)." (PMID 25894552, 2015). "In the tumor interstitial space, albumin-paclitaxel complexes bind to the Secreted Protein Acidic and Rich in Cysteine (SPARC), which is overexpressed in a majority of tumors, to achieve enhanced drug targeting and penetration in tumors." (PMID 26182353, 2015). "But about 7% of albumin and IgG accumulated in tumor and less than 10% accumulated in liver and spleen." (PMID 26284588, 2015). "Both groups were well balanced in terms of hemoglobin levels, serum levels of albumin, comorbidity, and tumor size." (PMID 25634099, 2015). "On POD 3, Hb, CRP, albumin administration on the postoperative day, lymph node involvement, SCr, and tumor site were effective variables." (PMID 26530188, 2015). "Given that the sizes of O2, glucose, and amino acids are smaller than that of LCFA (in complex with albumin), it is likely that areas with lipid starvation, hypoxia, expression of HIFs, and a nutrient supply exists in tumor tissues." (PMID 25879517, 2015). "Optimization of the chemical structure of antitumor photosensitizers (PSs) isaimed at increasing their affinity to a transport protein, albumin andirreversible light-induced tumor cell damage." (PMID 25927008, 2015). "Eventually, the albumin will be actively and selectively recognized and bound by the proteins-rich tumor tissues." (PMID 25915411, 2015). "On univariate analysis, age, Child-Pugh classification, tumor size, albumin, bilirubin, radiation dose, and AFP normalization were identified as significant parameters of OS." (PMID 26681337, 2015). "By performing a CO in vivo biodistribution measurement, we were able to show that albumin is an efficient CO carrier and specifically delivers CO to tumor sites." (PMID 25477186, 2015). "This process is characterized by the ability of macromolecules (>20 kDa), or small molecules bound to serum albumin, to accumulate in tumors as a result of their passive leakage from abnormal tumor vasculature." (PMID 26472022, 2015). "Target binding in tumor dominates that in plasma, with greater affinities (IC50 of 0.025 μM for HER2, and 0.029 μM for EGFR) that effectively extract albumin-bound lapatinib from blood passing through the tumor." (PMID 26571496, 2015). "In solid tumors, albumin seems to accumulate in the tumor microenvironment, and cancer cells seem to have the ability to utilize albumin as source of energy." (PMID 26457674, 2015). "Eastern Cooperative Oncology Group (ECOG score, p = 0.008), Child-Pugh classification (p = 0.012), albumin (p = 0.046), and hemoglobin (p = 0.028) were significant parameters that predicted primary tumor response to radiotherapy in multivariate analysis." (PMID 26072055, 2015). "The tumor inhibitory rates were 36.59% and 37.82% in mice receiving As2O3 and those receiving albumin-bound As2O3, respectively." (PMID 25915411, 2015). "Maximum tumor size (>5 cm) and low albumin (≤3.4 g/dL) were poor prognostic and disease progression factors in the HAIC group." (PMID 26044168, 2015). "A small change in molecular weight led to substantial differences in pharmacokinetics and systemic clearance, illustrated by the superior, yet delayed tumor uptake of streptavidin and albumin compared to Fab." (PMID 25901755, 2015). "Being albumin-bound, nab-paclitaxel uses the gp60 and caveolae-mediated albumin transport pathway to traverse the endothelial lining of blood vessels entering the tumor interstitium where it is trapped by SPARC." (PMID 25202467, 2014). "Univariate analysis identified the following prognostic factors that predicted increased risk of mortality: tumor size, serum AFP level ≥400 ng/ml, serum ALT level, serum albumin level and TACE treatment." (PMID 25541684, 2014).
tumor (continued). "In summary, IC7-1-Bu exhibited fluorescence localized to mitochondria dependent on Δψm, which enabled clear in vivo tumor imaging via serum albumin as a drug carrier for effective tumor targeting." (PMID 24737784, 2014). "We first tested the effect of three doses of 60 and 30 mg/kg of Nab-paclitaxel on body weight and tumor growth using tumors transplanted in nude mice (to avoid the potential immunogenic effect of the human albumin present in Nab-paclitaxel)." (PMID 24912774, 2014). "Considering the enhanced permeation and retention effect and the accumulation of albumin in the tumor interstitium, the development of albumin as a drug carrier is increasingly important to consider in terms of the targeted delivery of cancer therapy." (PMID 25161624, 2014). "It has been shown that albumin markedly accumulates in tumor tissues due to leaky capillary combined with a defective lymphatic drainage system in tumor interstitium which is known as enhanced permeation and retention (EPR) effect." (PMID 24895635, 2014). "It has been postulated that the ability of SPARC to bind albumin in the tumor interstitium enhances the accumulation of albumin-bound drugs within the tumor space." (PMID 25161624, 2014). "The presence of high amounts of albumin at the site of tumors and inflamed tissues has been utilized for tumor targeting by chemical conjugation of drugs to albumin." (PMID 25674083, 2014). "IC7-1-Bu showed fluorescence localized to the mitochondria of HeLa cells that was dependent on Δψm and also enabled clear in vivo tumor imaging via serum albumin as a drug carrier for effective tumor targeting." (PMID 24737784, 2014). "Albumin distribution around the infusion site was asymmetric for all the times simulated with high concentration inside the tumor." (PMID 24619021, 2014). "They show the non-uniform nature of the distribution and the tangential flux of albumin tracer along the skin boundary near the tumor." (PMID 24619021, 2014). "It was reported that peptide defensins released by granulocytes can contribute to extracellular cytotoxicity against various tumour targets but are markedly inhibited by albumin and other macromolecular serum components." (PMID 24915193, 2014). "The serum albumin levels of the rats in the tumour-bearing group (W) were reduced by approximately 31% compared to those in group LW (P < 0.0001), which had a similar value to that of the control group." (PMID 24383706, 2014). "For the chosen threshold value, albumin was distributed to approximately 48% of the tumor volume after one hour of infusion at 0.3 μL/min." (PMID 24619021, 2014). "A distinct characteristic of cancer tissue is a decrease in tumor endothelial barrier function which enhances the leakage of plasma macromolecules like albumin into the extracellular fluid which is coupled with a lack of a functional lymphatic drainage." (PMID 25193858, 2014). "The variables evaluated included age, gender, serum albumin, haemoglobin, body mass index, grade of tumour, response to NACT, drug regimen, dose intensity, and local treatment." (PMID 24900922, 2014). "With the natural affinity of albumin to tumor cells, it enablespaclitaxel to be concentrated in cancer lesion to exert bigger anti-neoplasticeffect." (PMID 25239521, 2014). "This albumin-based particle composition of paclitaxel is the first biologically interactive form of the drug with the potential to exploit a receptor-mediated pathway, allowing increased transport of albumin-bound paclitaxel from blood to tumor." (PMID 29147404, 2014). "Gary Cromwell for mouse tumor inoculation, Dr. Noriko Mori for the preparation of the albumin-Gd-DTPA used in this study, and Ms." (PMID 24466160, 2014). "At 2 weeks following tumor inoculation a slight increase in albumin staining was noted in the peritumoral area." (PMID 24818961, 2014).
tumor (continued). "Patients in group A had a greater incidence of low albumin, perioperative transfusion, minor resection, tumor size larger than 3 cm, multiple tumors, microvascular invasion, and Edmondson-Steiner grade III to IV." (PMID 24961934, 2014). "Using an Evans Blue–albumin complex, Matsumura and Maeda visualised and quantified tumour-specific passive accumulation in a Sarcoma 180 model (32 % dose/g tumour at 48 h)." (PMID 23797686, 2013). "An important feature of HSA is its ability to cross vascular endothelial cells through albumin-mediated transcytosis and accumulate in the interstitial space of tumor tissues, a process known as the enhanced permeability and retention (EPR) effect." (PMID 24278348, 2013). "The longer time that it takes Evens blue-Albumin to extravasate from tumor vessels into tumor parenchyma indicates the less abnormal tumor vascular hyperpermeability." (PMID 23799045, 2013). "Widespread albumin immunoreactivity was evident throughout the brains in animals that grew tumours after receiving CRCTU Walker 256 cells by the internal carotid artery injection or via direct inoculation into the brain." (PMID 23374226, 2013). "The xenograft model was additionally analyzed with respect to permeability to endogenous albumin, tumor size, and vascularization." (PMID 24175095, 2013). "While the effect of water exchange on the dynamic contrast enhanced (DCE) MRI parameters is well known, the model in this study assesses albumin-(GdDTPA) kinetics within the extravascular space of the tumor." (PMID 23650550, 2013). "Here, we show that the EPR effect is present in the U87 mg intracranial xenograft model by means of the accumulation and retention of endogenous mouse albumin and liposomes in the tumor interstitium." (PMID 24175095, 2013). "We then examined the tumor vascular permeability to macromolecules by intravital microscopy which allowed us to observe the diffusion of Evans blue-Albumin (molecular weight about 67 kD) from tumor vessel into tumor parenchyma." (PMID 23799045, 2013). "This was running in line with prior reports suggesting that SPARC improves intra-tumor concentration of paclitaxel when an albumin-bound preparation is used given the high affinity of SPARC to albumin." (PMID 23638089, 2013). "The visualization of the vascular network using labelled albumin showed that CT26 tumours were highly vascularized and disorganized." (PMID 23936648, 2013). "In the 1950s and 1960s, radio-iodinated albumin and albumin aggregates were used clinically to image tumours." (PMID 23797686, 2013). "It is likely that albumin immunoreactivity was increased in response to the substantial tumour growth evident in the CRCTU Walker 256 tumour inoculated groups and subsequent increased BBB permeability." (PMID 23374226, 2013). "EMC-Arg-Arg-Ala-Leu-Ala-Leu-DOX bears maleimide, which can rapidly and selectively react in situ with the cysteine-34 position of circulating albumin after intravenous administration and release the drug at the tumor site." (PMID 23291656, 2013). "Evans blue was combined with albumin and formed Evans blue-Albumin as soon as it was injected into tumor vessels." (PMID 23799045, 2013). "Our findings demonstrated that albumin nanospheres containing zinc-phthalocyanine tetrasulfonate were indeed efficient in mediating PDT for tumor remission, in very good agreement with the literature." (PMID 24341795, 2013). "Albondin receptor on the endothelial cells of tumor vassels allows transcytosis of albumin across continuous endothelium while overexpressed SPARC results in accumulation of albumin within the tumor interstitium." (PMID 23344060, 2013). "After multivariate analysis, serum albumin (P = 0.0498), Child–Pugh grade (P < 0.0001), tumor size (P = 0.0034), and number of tumors (P = 0.0491) were found to be independent predictors of overall survival." (PMID 22710886, 2013).